EEF1A1 (eukaryotic translation elongation factor 1 alpha 1)
Diseases named in the same sentence as EEF1A1 in open-access papers (continued):
Sharing a sentence is not in itself a finding about the gene and the disease.
prostate carcinoma (14 papers, 2010 to 2026). A carcinoma that arises from epithelial cells of the prostate gland. "We used the previously established IHC method to assess the protein expression of eEF1A1 in prostate cancer tissues with Gleason 4–6 (grade group I, low risk) and Gleason 7–8 (grade group II–IV, intermediate to high risk)." (PMID 35456960, 2022). "Our study aimed to investigate eEF1A1 as a biomarker for high-risk prostate cancer and to highlight the possible mechanism of eEF1A1 involvement in tumour progression." (PMID 35456960, 2022). "According to previous studies, EEF1A1 is associated with drug resistance in prostate cancer." (PMID 38965582, 2024). "Eukaryotic translation elongation factor 1 alpha 1 (eEF1A1) has been identified as a potentially useful serum biomarker for the metastatic progression of human prostate cancer." (PMID 39189262, 2024). "To investigate the role of eEF1A1 in the maintenance of aggressive prostate cancer cells, we used the prostate cancer cell line PC-3 cells, which has been described as androgen-independent with a highly undifferentiated phenotype, thus mimicking CRCP cells." (PMID 35456960, 2022). "In contrast to eEF1A2, the contribution of eEF1A1 to the phenotypic and molecular changes in human prostate cancer is far less clear." (PMID 35456960, 2022). "In this study, we have showed, for the first time, that actin-bound eEF1A1 maintains the viability of the aggressive prostate cancer cells." (PMID 35456960, 2022). "Taken together, the reported data indicate the important role of the eEF1A1–actin network in the maintenance of advanced prostate cancer." (PMID 35456960, 2022). "Although the eukaryotic elongation factor eEF1A1 plays a role in various tumours, there is little information on its prognosis/therapeutic value in prostate carcinoma." (PMID 35456960, 2022). "In the present study, we investigated the potential of eEF1A1 in sustaining the growth of PC-3 androgen-independent prostate cancer cells representative of CRCP." (PMID 35456960, 2022). "Despite the small number of patients, this study strongly suggests that eEF1A1 overexpression plays a role as a marker of prostate cancer aggressiveness as evidenced by recurrence and high score." (PMID 35456960, 2022). "The expression of eEF1A1 protein was determined in formalin-fixed, paraffin-embedded prostate cancer and hyperplasia tissue by IHC." (PMID 35456960, 2022). "We have found that eEF1A1 protein is overexpressed in advanced prostate cancer tissues, and especially in high-grade cancer cells with respect to low grade tumours." (PMID 35456960, 2022). "The novelty of this work, however, is that in prostate cancer, this appears to be due to the eEF1A1–actin complex." (PMID 35456960, 2022). "Formalin-fixed, paraffin-embedded tissue samples from 72 patients with prostate cancer and hyperplasia were analysed for protein expression of eEF1A1." (PMID 35456960, 2022). "Here, we dissect the contribution of the two constitutive forms, that is, eEF1A1 and eEF1A2 in prostate cancer." (PMID 22095224, 2012). "Here, we focus on the expression of EEF1A1/A2 in a panel of human prostate cancer cells demonstrating that the switch-on of EEF1A2 gene expression associates with prostate cell transformation." (PMID 22095224, 2012). "In conclusion, the results here presented support the concept that EEF1A2 switch-on is a feature of prostate cancer, assigning to EEF1A1 a minor involvement as potential marker of cancer." (PMID 22095224, 2012). "The biomarker leads identified in our ‘discovery’ phase study, including eEF1A1 are discussed in relation to their significance to prostate cancer progression." (PMID 22355332, 2012). "Our finding of increased eEF1A1 expression in osteoblasts in the vicinity of metastatic prostate cells, is in line with previous reports indicating a cross-talk between prostate cancer cells and osteoblasts during bone metastasis." (PMID 22355332, 2012).
prostate carcinoma (continued). "eEF1A1 also contributes to therapeutic resistance in prostate cancer." (PMID 39962586, 2025). "The eEF1A1–actin complexes appear to be critical for the viability of PC-3 cancer cells, suggesting that eEF1A1 may be an attractive target for therapeutic strategies in advanced forms of prostate cancer." (PMID 35456960, 2022). "Overexpression of the eEF1A1 protein can identify aggressive forms of prostate cancer." (PMID 35456960, 2022). "Further studies are needed to show that eEF1A1 may be an independent predictor of the pathological stage, metastatic disease, biochemical recurrence, and cancer-specific survival in prostate cancer." (PMID 35456960, 2022). "Finally, the data overall point to a relevant role of the eEF1A1–actin complex in sustaining the viability of aggressive prostate cancer cells." (PMID 35456960, 2022). "In PC-3 cells, used as a model for aggressive CRPC cancer, the aptamer GT75 can bind eEF1A1 in vitro, reduce cell viability, and promote cell detachment and autophagy, suggesting that eEF1A1 may be a therapeutic target for advanced prostate cancers." (PMID 35456960, 2022). "Therefore, in this study, we focused on the determination of eEF1A1 expression in human prostate cancer tissue and investigated the role of eEF1A1 in a poorly differentiated, hormone-independent cell line." (PMID 35456960, 2022). "Interestingly a truncated form of eEF1A1 known as prostate tumour inducing gene 1 (PTI-1) has been shown to be expressed in prostate carcinoma patient-derived blood samples and proposed to be a sensitive biomarker for prostate cancer." (PMID 22355332, 2012). "Eukaryotic elongation factor 1A2 switch-on, observed in cultured tumour prostate cells and in human prostate tumour samples, may represent a feature of prostate cancer; in contrast, a minor involvement is assigned to EEF1A1." (PMID 22095224, 2012). "To get more insight, we investigated the EEF1A1/A2 differential expression in a panel of prostate cancer cell lines: the androgen-responsive LNCaP and the non-responsive DU-145, PC-3 cells, described to display a low, moderate and high aggressive phenotype, respectively." (PMID 22095224, 2012). "However, the most evident result of our investigation is the dramatic up-regulation of the expression of EEF1A2, but not of EEF1A1, in the prostate cancer lines at the mRNA and protein levels, compared with the non-tumourigenic prostate PZHPV-7 cells." (PMID 22095224, 2012).
hepatocellular carcinoma (12 papers, 2015 to 2024). A malignant tumor that arises from hepatocytes. "Research suggests a strong association between EEF1A1 and poor prognosis in hepatocellular carcinoma, indicating its role as a pathogenic gene in this disease." (PMID 38965582, 2024). "To confirm the relationship of EEF1A1 to this phenotype, we used HepG2 human hepatoma cells stably expressing an shRNA targeting EEF1A1, which we previously demonstrated resulted in a modest knockdown (−24%)." (PMID 38272231, 2024). "Recently, eEF1A1 is reported as a pleiotropic protein and is highly expressed in many cancers, including hepatocellular carcinoma, renal cell carcinoma and gastric cancer." (PMID 37328464, 2023). "To characterize the expression of eEF1A-1 in response to lipid overload in vitro, we used HepG2 human hepatoma cells because, like intact human and rodent liver, and unlike other hepatocyte lines, they exclusively express the eEF1A-1 variant of eEF1A." (PMID 26102086, 2015). "In addition, EEF1A1 has been reported to control cell proliferation and cell cycle via activating MAPK signaling in colorectal cancer or STAT1 signaling in hepatocellular carcinoma." (PMID 37446017, 2023).
colorectal cancer (11 papers, 2010 to 2025). A primary or metastatic malignant neoplasm that affects the colon or rectum. "In previous reports, EEF1A1 has been associated with a poor prognosis in colorectal cancer and HCC." (PMID 38965582, 2024). "Through combining the analysis of cohorts in GEO database and in vivo and in vitro experiment, we report a novel oncogenic and prognostic role of eukaryotic elongation factor 1 A1 (eEF1A1) in colorectal cancer (CRC)." (PMID 35607944, 2023). "Oncomine analysis of colorectal cancer with the pre-specified thresholds didn’t return any datasets with significant difference in mRNA levels, for EEF1A1, EEF1A2, EEF1B2, EEF1G and EEF2." (PMID 29342219, 2018). "SurvExpress analysis revealed significantly reduced mRNA levels of EEF1A1, EEF1B2, EEF1E1, EEF1G and EEF2 in the high-risk group, in colorectal cancer and, predicted poor survival." (PMID 29342219, 2018). "Furthermore, eEF1A1 is one of ribosome pathway genes enriched in circulating tumor cells of colorectal cancer." (PMID 39962586, 2025). "For example, previous evidence supports that EEF1A1 may provide potential biomarkers for fecal RNA-based colorectal cancer screening." (PMID 28900297, 2017).
pancreatic cancer (10 papers, 2009 to 2025). "In pancreatic cancer, the mRNA levels of EEF1A1, EEF1A2, EEF1B2, EEF1D and EEF1E1 were found to be significantly downregulated, as shown by Oncomine analysis." (PMID 29342219, 2018). "Eukaryotic translation elongation factor 1 alpha 1 (EEF1A1) was overexpressed among the pancreatic cancer, leukemia and osteosarcoma cell lines, and siRNA treatment against EEF1A1 produced a chemosensitization toward MTX." (PMID 19732436, 2009). "Although it has been traditionally described as a cellular housekeeper enzyme, overexpression of EEF1A1 is found in melanomas and tumors of the pancreas, breast, lung, prostate and colon." (PMID 19732436, 2009). "Besides, utilizing 99 clinical specimens of pancreatic cancer patients, eEF1A1 protein levels are found positively correlated with pancreatic cancer stage but negatively correlated with patient survival." (PMID 37704601, 2023). "This highlights the importance of eEF1A1 in the progression of pancreatic cancer." (PMID 37704601, 2023). "Furthermore, it was shown that eEF1A1 plays a significant role in regulating pancreatic cancer cell stemness, its levels positively correlated with pancreatic cancer progression and negatively affecting patient survival." (PMID 36982256, 2023). "Specifically targeting eEF1A1, BE may serve as a promising lead for hypoxia target therapy in pancreatic cancer treatment." (PMID 37704601, 2023). "In contrast to the internal control gene EEF1A1, we observed the cycling threshold (Ct) for detecting ATP6V0B was statistically significant for EVs isolated from pancreatic cancer plasma and tumor tissue, when compared to the healthy cohort." (PMID 40598203, 2025).
COVID-19 (9 papers, 2020 to 2024). A disease caused by infection with severe acute respiratory syndrome coronavirus 2. "Our analysis found that the low expression of EEF1A1 may indicate COVID-19, and the dysfunction of EEF1A1 causes susceptibility to SARS-CoV-2 infection." (PMID 35928229, 2022). "Ultimately, EEF1A1, EGR1, UBA52, DDX5 and IRF8 might be the key shared pathogenesis-related genes in COVID-19 and asthma." (PMID 36575422, 2022).
gastric cancer (9 papers, 2019 to 2024). A primary or metastatic malignant neoplasm involving the stomach. "A recent study suggests that eEF1A1 is vital for the expression of IL-6 mediated by human oncostatin-M (OSM); however, currently there are very little information on the role of eEF1A1 in gastric cancer." (PMID 32636937, 2020). "In stomach cancer, EEF1A1 has been reported to promote gastric cancer cell migration and invasion." (PMID 31703307, 2019).
cervical carcinoma (6 papers, 2013 to 2026). A carcinoma arising from either the exocervical squamous epithelium or the endocervical glandular epithelium. "The genes SQLE, APOC1, H1.2, GCH1, and EEF1A1 were determined to be associated with cervical cancer." (PMID 41583517, 2026). "They found that S100A9, eEF1A1, PKM2, COPA and so on, may become candidate markers for early diagnosis of cervical cancer and new targets for therapy." (PMID 36498728, 2022).
colon carcinoma (6 papers, 2009 to 2024). "Additionally, the results of the current study revealed that EEF1A1 expression was associated with tumor location, and right-sided colon cancers tended to show lower expression of EEF1A1, although the correlation with tumor sidedness was not significant." (PMID 31703307, 2019). "Inhibition of eukaryotic translation elongation factor 1 alpha 1 by Nannocystin Ax has been reported to inhibit translation of new proteins and downregulate cyclin D1, inducing G1 cell cycle arrest in colon cancer cells." (PMID 38968330, 2024). "In colon cancer, EEF1A1 mRNA expression levels were significantly low in patients with a high risk of recurrence compared to those in patients with a low risk, which was also consistent with our findings." (PMID 31703307, 2019). "Among patients with stage III colon cancer, those with low EEF1A1 expression had a shorter OS than those with high EEF1A1 expression." (PMID 31703307, 2019). "Based on our results, high expression of EEF1A1 indicates a favorable survival prognosis for patients with colon cancer, and at the mRNA level, EEF1A1 was found to be downregulated in tumor tissues compared to that in normal tissues." (PMID 31703307, 2019). "Intestinal obstruction or perforation, due to primary colon cancer, was more frequently observed in patients with low EEF1A1 expression than in those with high expression." (PMID 31703307, 2019). "We determined the prognostic effect of EEF1A1 on human colon cancer." (PMID 31703307, 2019). "In the present study, we investigated EEF1A1 expression and its prognostic significance for patients with stage II and III colon cancer who underwent curative resection." (PMID 31703307, 2019). "Interestingly, based on our results, patients who did not undergo treatment for stage II colon cancer showed differences in OS according to EEF1A1 expression." (PMID 31703307, 2019).
ovarian carcinoma (6 papers, 2018 to 2024). A malignant neoplasm originating from the surface ovarian epithelium. "Oncomine analysis for ovarian cancer revealed significant difference of mRNA levels between tumor and normal samples, for EEF1A1, EEF1A2 and EEF1E1 only." (PMID 29342219, 2018). "Exceptionally, the TCGA dataset for ovarian cancer (TCGA–OV) showed a reduction in EEF1A2 and EEF1A1 expression compared with GTEx normal tissue, which could be due to other mutations, sample heterogeneity, normalization techniques or statistical methodologies, sample size, and clinical variations." (PMID 38172654, 2024).
prostate tumour (6 papers, 2009 to 2026). "Antisense-mediated abrogation of EEF1A1 expression inhibits tumorigenesis and anchorage-independent cell replication in prostate tumor cells." (PMID 19732436, 2009). "Interestingly, intense immunoexpression of eEF1A1 was seen in osteoblasts and in particular those osteoblasts in the vicinity of metastatic prostate tumour cells." (PMID 22355332, 2012). "Thus, it is tempting to speculate that eEF1A1 generally contributes to prostate tumour onset by means of its moonlighting functions, that is, cytoskeleton modulation, and possibly genes expression, but it unlikely signs cancer progression." (PMID 22095224, 2012).
osteosarcoma (5 papers, 2009 to 2023). A usually aggressive malignant bone-forming mesenchymal neoplasm, predominantly affecting adolescents and young adults. "Likewise, our findings indicate that the knockdown of EEF1A1 impedes cell proliferation and cyclin D1 expression in osteosarcoma, chondrosarcoma, and antler cartilage cells." (PMID 37446017, 2023). "Thus, it is plausible that the migratory ability of osteosarcoma, chondrosarcoma, and antler cartilage cells markedly declined with the inhibition of EEF1A1." (PMID 37446017, 2023). "CDK8, EEF1A1, and NTN1 have been confirmed as direct target genes of miR-PC-2869 in osteosarcoma cells, and their involvement in the pathogenesis of various human cancers has been previously reported." (PMID 37446017, 2023). "Thus, we hypothesized that CDK8, EEF1A1, and NTN1 mediate the tumor-suppressor activity of miR-PC-2869 in osteosarcoma cells." (PMID 37446017, 2023).
Parkinson disease (5 papers, 2016 to 2025). A progressive degenerative disorder of the central nervous system characterized by loss of dopamine producing neurons in the substantia nigra and the presence of Lewy bodies in the substantia nigra and locus coeruleus. "EEF1A1 has demonstrated involvement in the regulation of genes associated with the neuroinflammatory process in Parkinson’s disease." (PMID 38540795, 2024). "eEF1A1 is also implicated in neuroinflammation of AD and Parkinson’s Disease." (PMID 39962586, 2025). "Finally, although the EEF1A1, RPL12 and RPL15 genes have not been directly linked to ALS, they have been associated with other neurological diseases, such as Parkinson’s and Alzheimer’s." (PMID 38540795, 2024).
Alzheimer disease (4 papers, 2021 to 2023). A progressive, neurodegenerative disease characterized by loss of function and death of nerve cells in several areas of the brain leading to loss of cognitive function such as memory and language. "Several publications showed a decreased expression of eEF1A1 in Parkinson’s or Alzheimer’s disease patients." (PMID 38139189, 2023). "Current research on DCTN1-AS1 has mainly focused on the immune direction of Alzheimer's disease, with DCTN1 possibly physically connecting the EEF1A1-recognized cytoplasmic aggregates to the power protein motor and participating in the retrograde transport of the microtubule cargo." (PMID 35401751, 2022).
liver cancer (4 papers, 2018 to 2025). An epithelial or non-epithelial malignant neoplasm that arises from the liver. "RNF12 might interact with EEF1A1 and regulate the enzymatic delivery of aminoacyl tRNAs to the ribosome, which promotes the progression of liver cancer." (PMID 37132043, 2023).
melanoma (4 papers, 2009 to 2025). A malignant, usually aggressive tumor composed of atypical, neoplastic melanocytes. "Two proteins interacting with 14-3-3, PHB and EEF1A1, were co-detected in both GCMN and melanoma proteomes." (PMID 22906024, 2012).
adenoma (3 papers, 2012 to 2022). A neoplasm arising from the epithelium. "Pilot evaluation in archive prostate tissues showed the presence of EEF1A2 mRNA in near all neoplastic and perineoplastic but not in normal samples or in benign adenoma; in contrast, EEF1A1 mRNA was everywhere detectable." (PMID 22095224, 2012). "According to these criteria, the following five pairs of miRNAs/mRNAs were retained among 57 pairs in the adenoma samples: hsa-miRNA-34a-5p/SLC12A2 (solute carrier family 12 member 2), hsa-miRNA-15b-5p/SLC12A2, hsa-miRNA-195-5p/SLC12A2, hsa-miRNA-15a-5p/SLC12A2, and hsa-miRNA-3907/EEF1A1." (PMID 35875068, 2022). "Notably, in a fresh prostate benign adenoma sample, EEF1A1 but not EEF1A2 expression was detected, further stressing the concept that EEF1A2 switch-on occurs in neoplastic tissue." (PMID 22095224, 2012).